CD4 (CD4 molecule)
Diseases named in the same sentence as CD4 in open-access papers (continued):
Sharing a sentence is not in itself a finding about the gene and the disease.
AIDS (continued). "We consider the epigenetically regulated memory CD4 T-cells and the CD4 T-cell helped CD8 T-cell function to be the foundation of an AIDS cure, either sterile or functional." (PMID 24151495, 2013). "The CD4 nadir of the cohort ranged from 6 to 755 cells/μL, and 8 patients had a history of an AIDS diagnosis." (PMID 23737751, 2013). "Especially for the new recombinants infections, they all have low CD4 cell counts (<500 cells/μL) and more than 50% had obvious AIDS-like symptoms." (PMID 23372706, 2013). "It is the dual role of memory CD4 T-cells in HIV infection that lays down the unique challenge for HIV/AIDS eradication and cure." (PMID 24151495, 2013). "During 30 years of research on human immunodeficiency virus (HIV), our knowledge of its cellular receptors - CD4, CCR5 and CXCR4 - has illuminated aspects of the pathogenesis of the acquired immune deficiency syndrome (AIDS)." (PMID 23692808, 2013). "Patients who started HAART with a CD4<200 cells/mL were 62.1% more likely to die or have an AIDS-defining event during follow-up (95% CI 1.08, 2.43) when compared to those who started with a CD4>500." (PMID 23658717, 2013). "We chose to focus on persons living with AIDS who had CD4 T-lymphocyte counts fewer than 200 cells/mL or percentage below 14 because these measurements represent immunological AIDS with its accompanying heightened risk for opportunistic infections." (PMID 24124447, 2013). "Primary endpoint was clinical failure at 3 years, defined as death, new AIDS-defining event, or CD4 <50 cells/mm3." (PMID 23940461, 2013). "Increased mortality was observed among patients with sepsis as etiology of respiratory failure (HIV related and non-AIDS related), in those receiving mechanical ventilation, and in patients with decreased CD4 cell count." (PMID 24065988, 2013). "Low category of BMI was associated with lower CD4 count and serum selenium concentration among HIV/AIDS patients at diagnosis." (PMID 24198891, 2013). "By 2010, ART reached 70% of the estimated number of people living with HIV/AIDS with CD4<350/mm3, with progressively improving patient retention and survival." (PMID 23922711, 2013). "Late HIV diagnosis (initial CD4 cell count <350 or AIDS within 3 months of HIV diagnosis) applied to 81% of patients who were first diagnosed HIV positive during the study period and who required ICU admission." (PMID 23331544, 2013). "The median CD4+ T cell count of those who developed a new AIDS-defining condition was 25/mm3 (range: 1–90) at entry and 13/mm3 (range: 0–127) at the visit before the new AIDS-defining condition diagnosis." (PMID 24260125, 2013). "Deaths were considered AIDS related, if CD4 count <6 months before death was <200 cells/μL and/or an AIDS-related event occurred <12 months of death." (PMID 23431117, 2013). "By December 2010, of the 278 cases, 62% had progressed to CD4 count ≤250 and 32% to AIDS, while 34% had died." (PMID 23951241, 2013). "In high-income countries, about a quarter to a third of people with HIV are diagnosed late, with a CD4+ T-lymphocyte count of <200 cells/μL or an illness that defines the acquired immunodeficiency syndrome (AIDS)." (PMID 24223724, 2013). "It is worthwhile noting that in this setting antiretroviral therapy was only recommended in patients with CD4+ counts less than 200 or having an AIDS-defining illness (WHO stage IV)." (PMID 23855622, 2013). "Overall the groups were similar in regard to race, initial median CD4 count, prevalence of AIDS, and being on HAART at presentation." (PMID 24106419, 2013). "The diagnosed AIDS case rate, CD4 T-cell counts, HIV subtypes, and origin of the recombinant strains were investigated in 138 collected samples." (PMID 23372706, 2013). "ART was started in 295 patients, in 30 patients AIDS was diagnosed, and in 14 patients CD4 cell count declined to below 100 cells/mm3." (PMID 23724048, 2013).
AIDS (continued). "Potent combination antiretroviral therapy (ART) leads to suppression of the viral load, and immune reconstitution, usually defined by an increase in CD4+ T cell (CD4) count, and consequently, to a reduction in occurrence of AIDS and mortality." (PMID 24013838, 2013). "Nearly a third (29.4%) had a baseline CD4 count of <200 cells/μL or an AIDS diagnosis based on opportunistic illness." (PMID 24391937, 2013). "With the use of ART, mortality due to serious non-AIDS events (SNAEs) has become more prominent especially in resource-rich settings and in patients with higher CD4 T cell counts." (PMID 24330529, 2013). "In such model, HIV/AIDS infected individuals are divided into 13 different stages according to CD4+ level, and at each stage people have a specific infection rate." (PMID 24195071, 2013). "The HIV/AIDS patients presented low CD4 cell counts (72 cells/mm3), and 17 (57%) patients were on HAART before hospital admission." (PMID 23874739, 2013). "The depletion of CD4 cells in our patient was similar to that observed in AIDS patients, in which bacillary angiomatosis was first described in the 80s of the past century." (PMID 23710386, 2013). "The accurate determination of CD4 T cells is of crucial clinical importance for caring adults or children infected with HIV or suffering from AIDS." (PMID 23631664, 2013). "The purpose of this study is, therefore, to describe the prevalence and pattern of ocular manifestation among HIV/AIDS patients and determine correlation with the CD4+T cell count." (PMID 23710936, 2013). "Patients with AIDS and low CD4 count < 200 also had a LOS of eight days (median range 4 -61 days) compared to three days (2 - 61days), P = 0.03 via t-test comparison." (PMID 23390470, 2013). "Candidia esophagitis (CE) is an AIDS-defining condition, usually occurring in individuals with low CD4 counts of <200 cells/μL." (PMID 23555571, 2013). "In 2009–2010, the level of ART initiation in patients with CD4 cell count ≤350 cells/mm3 was still suboptimal (73%); fortunately during this period all patients with clinical AIDS or CD4 cell count ≤200 cells/mm3 had timely initiation of ART." (PMID 23936509, 2013). "This, combined with previously reported significant differences between males and females in CD4 T cell counts at AIDS onset, indicate sex-related differences exist in certain aspects of HIV-related immune dysfunction." (PMID 23365694, 2013). "CD4 T cells play a central role in human immune protection and its importance is clearly demonstrated in AIDS patients." (PMID 23638187, 2013). "Patients needing ICU admission were older, more often female and diagnosed with AIDS, they more often had a history of IV drug use and lower CD4 cell counts at cohort entry." (PMID 23331544, 2013). "In our study all the monkeys maintained normal CD4 counts but exhibited other signs of AIDS including SIV-viremia, wasting and lymphadenopathy." (PMID 23402317, 2013). "The role of CD4+ T cells measurements has been renewed in recent years in sub-Saharan Africa as a result of the HIV/AIDS pandemic." (PMID 23710648, 2013). "Overall, 58 patients (30 in the VL arm and 28 in the CD4 arm) reached the primary endpoint of clinical failure: three experienced a CD4 count decrease below 50 cells/mm3, 33 developed a new AIDS-defining event (including nine followed by death), and 22 died." (PMID 23940461, 2013). "AIDS Patients with low CD4+ T-cell counts (<50 cells/μL) accounted for 23.4%, and 68.94% of patients received HAART." (PMID 24376638, 2013). "At diagnosis, 162 (16%) had had an AIDS-defining event and 308 (31%) a CD4 cell count <200 cells/mm3." (PMID 23638870, 2013). "The mechanisms by which SIV-infected SMs avoid AIDS are complex and only partly understood, but appear to be related to the absence of chronic immune activation and the relative preservation of CD4+ central-memory T cells from direct virus infection." (PMID 24009514, 2013).
AIDS (continued). "The median CD4+ T cell count for those who reported a new serious non-AIDS-defining event was 15/mm3 (range: 0–89) at entry and 9/mm3 (range: 0–135) at the visit prior to the new serious non-AIDS-defining event." (PMID 24260125, 2013). "Patients with CD4 counts under 200 at diagnosis have much higher mortality rates and are more likely to be diagnosed with an AIDS-defining illness." (PMID 23626808, 2013). "The mechanisms leading to the activation and depletion of CD4+ lymphocytes are of particular interest since their maintenance is critical in staving off the onset of AIDS." (PMID 23442890, 2013). "Overall, the recommendation was to defer ART initiation until CD4 counts decline to <350 cells/μl or an AIDS-defining illness develops (clinical stage 3 or 4, as per WHO clinical staging classification of HIV disease)." (PMID 23767777, 2013). "Studies have suggested the linkage between weight loss induction, depletion of CD4 count and of serum selenium in HIV/AIDS." (PMID 24198891, 2013). "The purpose of this study was to determine the patterns of ocular manifestations of HIV/AIDS and their correlation with CD4+Tcells count." (PMID 23710936, 2013). "Kaposi's sarcoma (KS) is among the most common cancers in AIDS patients, especially in African countries, and occurs at all CD4 levels below 500 cells/mm3." (PMID 23936695, 2013). "Of particular interest is that AIDS events have been described also in few EC experiencing drop in CD4+ T cell count despite maintaining undetectable viral load." (PMID 23577012, 2013). "Cox proportional hazard regression modelling was used to estimate adjusted hazard ratios (aHRs) of progression to: CD4≤250, AIDS onset and death, adjusted for sex, age and CD4 count at enrolment." (PMID 23951241, 2013). "We conclude that immune activation is most likely the main cause of CD4+ T-cell depletion, loss of HIV-specific immunity and HIV-associated non-AIDS disease, also in patients on cART." (PMID 24133492, 2013). "At the level of HIV/AIDS eradication and cure, however, the techniques and methodologies for studying of HSPCs should be utilized to study memory CD4 T-cells, peculiarly for translational research and multidisciplinary collaborative studies." (PMID 24151495, 2013). "AIDS is characterized by the selective targeting of the CD4+/CD8+ T cells by HIV which fatally impairs the immune system." (PMID 23483108, 2013). "The groups had similar CD4+ counts, prevalence of AIDS, and use of antiretrovirals (ARV) at initiation of obstetrical care." (PMID 24106419, 2013). "They divided the diagnosed HIV-positive individuals into 5 stages based on the CD4+ T cell counts in the blood (above 500, 350–499, 200–349, below 200 copies, and AIDS stage)." (PMID 24195071, 2013). "In our study 40.00% of patients in AIDS (64 patients), while 26.87% in non–AIDS (43 patients), as we were able to do CD4 count only in 107 patients out of 160 patients." (PMID 23795271, 2013). "Among the 13 PHIV with a diagnosis of AIDS or CD4 <350 at entry into OB care, only 5/13 (38%) were on HAART." (PMID 24106419, 2013). "Median CD4 cell counts at baseline for patients who died of AIDS-related infections and AIDS-related malignancies were, respectively, 117 and 146 cells/mm3, as opposed to 296 cells/mm3 for patients who died of non-AIDS related causes." (PMID 23577074, 2013). "Other studies, mostly from western Europe, estimated that 24-39% of HIV-infected patients presented for care at an advance stage of the disease (with AIDS and/or CD4 cell count <200/mm3)." (PMID 23638870, 2013). "An early study from the CASCADE group suggested that 15 and 7% of elite controllers infected with HIV for more than 16 years had CD4 cell counts less than 350 cells/μl or AIDS, respectively." (PMID 23698562, 2013). "AIDS patients with more CD4+ T-cells within 6 months at diagnosis (cell/μL) presented lower risk of death (HR = 0.29 for 50- vs <50, 95% CI, 0.15–0.59, P = 0.001)." (PMID 24376638, 2013).
AIDS (continued). "The CD4 levels of all patients were less than 350 cells/μl when they were enrolled in the Pediatric AIDS Clinical ARV Trial Group." (PMID 23468942, 2013). "Human immunodeficiency virus type 1 (HIV-1) infects and destroys cells of the immune system, which ultimately leads to CD4+ T-cell depletion and a profound immune deficiency known as Acquired Immunodeficiency Syndrome (HIV/AIDS)." (PMID 24146801, 2013). "AIDS patients with low CD4+ cell counts incur higher expenditures in the first year of antiretroviral treatment, due to high incidence of adverse drug events and opportunistic infections." (PMID 24489581, 2013). "Nearly 54% of the participants were late presenters—individuals who had a CD4 count of less than 350 cells/mm3 or an AIDS-defining illness within 6 months of HIV diagnosis." (PMID 24137103, 2013). "The Gastrointestinal (GI) tract plays a pivotal role in AIDS pathogenesis as it is the primary site for viral transmission, replication and CD4+ T cell destruction." (PMID 23593167, 2013). "Primary outcomes (clinical failure) at 3 y: death, new AIDS-defining events, or confirmed CD4 <50/mm3." (PMID 23940461, 2013). "SPVL is an early prognostic indicator for AIDS, as it varies by orders of magnitude between individuals, with high values having faster CD4 cell decline, progressing more rapidly to AIDS and death." (PMID 24481201, 2013). "We examined factors associated with ICU admission in multivariate time-updated models incorporating age, gender, HIV risk group, AIDS (CDC-C), use of cART and most recent CD4 cell count." (PMID 23331544, 2013). "In the absence of effective antiretroviral therapy, as was the case of child 2, increased replication of the Nab-resistant X4 isolates likely contributed to rapid CD4+ T cell depletion and progression to AIDS." (PMID 24156513, 2013). "In resource-limited settings, patients present far later for care, on average with a CD4 cell count of <200 cells/mm3 or with an AIDS-defining event; 20–40% start ART with a CD4 of <100 cells/mm3." (PMID 24314398, 2013). "As already mentioned, destruction of CD4-positive T-helper lymphocytes was highlighted in an early report of the nature of the immunodeficiency, which was subsequently called AIDS." (PMID 23692808, 2013). "Nevertheless, our mortality estimates associated with immediate ART initiation or starting ART at a high CD4 value are consistent with the probability of experiencing AIDS or death found in both the immediate and deferred ART arms of the PREDICT trial." (PMID 24260029, 2013). "The results of the current study reveal that the majority of newly diagnosed HIV positive patients in China had an initial CD4 count consistent with an AIDS diagnosis." (PMID 24024658, 2013). "Ocular TB is found in all CD4 count ranges, and asymptomatic choroidal tubercles are among the commonest manifestations of ocular TB in AIDS." (PMID 23514612, 2013). "Several studies suggested that low immune activation and relative resistance of CD4+ central memory T-cells from virus infection are mechanisms that protect SMs from AIDS." (PMID 24009514, 2013). "Progression to AIDS occurs when any severe AIDS-defining condition is diagnosed, when the CD4 count in the blood falls below 200 cells/mm3, or when CD4 cells account for fewer than 15% of lymphocytes." (PMID 24137103, 2013). "During both the pre-ART and whole periods, higher baseline CD4 cell count offered protection against progression to AIDS at a significant adjusted rate of 17% during the pre-ART period (Part 2)." (PMID 23951241, 2013). "An imbalance between production and destruction of peripheral CD4+ T cells leads to their progressive decline over time and eventually to AIDS." (PMID 24237970, 2013). "HIV-AIDS is characterised by a profound immunodeficiency resulting from the depletion of CD4+ T helper lymphocytes." (PMID 24295071, 2013).
AIDS (continued). "The study population had advanced HIV/AIDS (median CD4+ T-lymphocyte count 60 cells/μl [IQR 22–200 cells/μl]), but only 15 (16%) patients were receiving anti-retroviral therapy." (PMID 22745833, 2012). "Mean baseline CD4 count for AIDS patients were all less than 250 cells/mm3, with TDF+3TC+EFV patients having the lowest CD4 count; increases in CD4 counts were similar for all AIDS patients at 6 and 12 months after starting all ART regimen." (PMID 23118869, 2012). "K130N resulted in an additional PNGS and its appearance in the main viral population coincided with a consistently low CD4 count and the development of AIDS." (PMID 22427893, 2012). "Further, modelling age, hepatitis B and C status, hypertension, anaemia, CD4 count, year of follow-up and on cART viral load as time updated covariates the rate of AIDS related mortality was more than three times higher in East Europe compared to South." (PMID 22911841, 2012). "CD4 cell count of ≤ 200 cell/μ L is vital marker in the management of HIV/AIDS patients; it is at this stage that antiretroviral therapy (ART) is started and co-trimoxazole prophylaxis is required." (PMID 22793790, 2012). "Higher levels of CD8 memory T cells (CD8+,CD45RO+,CD45RA-) showed a significant beneficiary effect on survival, HR of 0.95 (95% confidence interval 0.91–0.99, P = 0.016) when adjusted for age, nadir CD4 count, CD4 count, and AIDS and hepatitis C status." (PMID 22815704, 2012). "In most industrialized countries about one-third of HIV-infected patients access the health care system with advanced HIV disease (CD4 cell count below 200/mm2 or AIDS), and one-half late (CD4 cell count below 350/mm3 or AIDS)." (PMID 23056308, 2012). "But there are very few reports on the diarrheal pathogens isolated in HIV/AIDS cases in relation to CD4 T lymphocyte counts and stool characteristics from New Delhi." (PMID 23326669, 2012). "We estimated CD4 cell loss in ART-naïve, AIDS-free individuals using mixed models allowing for random intercept and slope, and time from seroconversion to clinical AIDS, death and antiretroviral therapy (ART) initiation by survival methods." (PMID 22412867, 2012). "Patient CD4 counts, AIDS progression, and treatment histories were matched as closely as possible to patients in the brain-derived dataset and all virus was clade-B." (PMID 23166702, 2012). "The dramatic nature of this phenotype allowed us to investigate the role of Nef in two decisive phenotypes for the development of AIDS: maintenance of high levels of virus replication and depletion of CD4+ T cells and thymocytes." (PMID 22640559, 2012). "In EE, however, a larger proportion of patients started cART at CD4-cell count <200 cells/mm3 or at AIDS diagnosis in 2007 or later compared with ≤2004 (48% vs. 44%)." (PMID 23009317, 2012). "A randomized placebo controlled trial enrolled 102 patients infected with HIV and AIDS with CD4+ cell counts between 250 and 600 cells/mm3 who were treated with Aikang Capsule or placebo for 6 months." (PMID 23326295, 2012). "A mathematical model to predict the optimal dosing regimen for AIDS therapy has been reported, but in this case, CD4+ cell counts and knowledge of the adherence interval of individual patients is required to adjust the dose." (PMID 22481974, 2012). "Despite variability, the majority of HIV-1-infected individuals progress to AIDS characterized by high viral load and massive CD4+ T-cell depletion." (PMID 23243424, 2012). "As of their last eligible genotypic test, 49% had public insurance, 38% had a CD4+ cell count <200 cells/mm3, 80% had been diagnosed with AIDS by immunologic or clinical criteria, and the median HIV RNA was 4.3 log10 copies/mL at last eligible genotypic test." (PMID 22611484, 2012). "The depletion of CD4+ T cells, which is a main feature of AIDS, is certainly an important contributor to the increased risk of reactivation of latent TB and susceptibility to new M. tuberculosis infection." (PMID 22363214, 2012).